SLC3A2 (solute carrier family 3 member 2)
Description:
Acts as a chaperone that facilitates biogenesis and trafficking of functional transporters heterodimers to the plasma membrane. Forms heterodimer with SLC7 family transporters (SLC7A5, SLC7A6, SLC7A7, SLC7A8, SLC7A10 and SLC7A11), a group of amino-acid antiporters. Heterodimers function as amino acids exchangers, the specificity of the substrate depending on the SLC7A subunit. Heterodimers SLC3A2/SLC7A6 or SLC3A2/SLC7A7 mediate the uptake of dibasic amino acids. Heterodimer SLC3A2/SLC7A11 functions as an antiporter by mediating the exchange of extracellular anionic L-cystine and intracellular L-glutamate across the cellular plasma membrane. SLC3A2/SLC7A10 translocates small neutral L- and D-amino acids across the plasma membrane (By similarity). SLC3A2/SLC75 or SLC3A2/SLC7A8 translocates neutral amino acids with broad specificity, thyroid hormones and L-DOPA. SLC3A2 is essential for plasma membrane localization, stability, and the transport activity of SLC7A5 and SLC7A8. When associated with LAPTM4B, the heterodimer SLC7A5 is recruited to lysosomes to promote leucine uptake into these organelles, and thereby mediates mTORC1 activation. Modulates integrin-related signaling and is essential for integrin-dependent cell spreading, migration and tumor progression. (Microbial infection) In case of hepatitis C virus/HCV infection, the complex formed by SLC3A2 and SLC7A5/LAT1 plays a role in HCV propagation by facilitating viral entry into host cell and increasing L-leucine uptake-mediated mTORC1 signaling activation, thereby contributing to HCV-mediated pathogenesis. (Microbial infection) Acts as a receptor for malaria parasite Plasmodium vivax (Thai isolate) in immature red blood cells.
Synonyms: 4F2hc; CD98; MDU1; 4T2HC; 4F2; NACAE; CD98HC
Tractability: Small molecule: a structure with a bound ligand is known. Antibody: UniProt places it where antibodies can reach, with high confidence; its Gene Ontology location is reachable by antibodies, with high confidence; UniProt predicts a signal peptide or a membrane-spanning region. PROTAC: UniProt records ubiquitination sites on it; ubiquitination databases record sites on it; its protein half-life has been measured.
Gene: Protein-coding gene on chromosome 11 (62,855,970 to 62,888,910, forward strand). Ensembl gene ENSG00000168003.
Subcellular location: Apical cell membrane; Cell membrane; Cell junction; Lysosome membrane; Melanosome; Basolateral cell membrane
Subcellular location (Human Protein Atlas): Nucleoplasm; Plasma membrane
Pathways (Reactome):
Disease: Defective amino acid transport by SLC7A7 causes lysinuric protein intolerance (LPI)
Hemostasis: Basigin interactions
Metabolism: Tryptophan catabolism
Transport of small molecules: Amino acid transport across the plasma membrane
Gene Ontology:
Molecular function: aromatic amino acid transmembrane transporter activity; cadherin binding; double-stranded RNA binding; exogenous protein binding; L-alanine transmembrane transporter activity; L-leucine transmembrane transporter activity; neutral L-amino acid transmembrane transporter activity; protein binding; protein heterodimerization activity; RNA binding; protein homodimerization activity
Biological process: amino acid import across plasma membrane; isoleucine transport; L-alanine import across plasma membrane; L-histidine transport; L-leucine import across plasma membrane; L-leucine transport; methionine transport; phenylalanine transport; proline transport; response to exogenous dsRNA; symbiont entry into host cell; thyroid hormone transport; tryptophan transport; tyrosine transport; valine transport; amino acid transport; calcium ion transport; transport across blood-brain barrier; carbohydrate metabolic process
Cellular component: amino acid transport complex; apical plasma membrane; basolateral plasma membrane; cell surface; extracellular exosome; lysosomal membrane; melanosome; membrane; plasma membrane; transmembrane transporter complex; anchoring junction; basal plasma membrane; apical pole of neuron; neuronal cell body; synapse
Genetic constraint (gnomAD): Loss-of-function variants: 32 observed, 47.38 expected, observed/expected ratio (o/e) 0.68, 90% interval 0.51 to 0.91. The upper end of that interval is the gene's LOEUF score, 0.91, which puts it in group 3 of 6, group 1 being the genes least tolerant of losing a copy. Missense variants: 587 observed, 677.37 expected, observed/expected ratio (o/e) 0.87, 90% interval 0.81 to 0.93. Synonymous variants: 277 observed, 291.72 expected, observed/expected ratio (o/e) 0.95, 90% interval 0.86 to 1.05.
Homologues: Orthologues: chimpanzee SLC3A2 (99% identical), macaque SLC3A2 (96% identical), rabbit SLC3A2 (83% identical), pig SLC3A2 (81% identical), dog SLC3A2 (81% identical), rat Slc3a2 (76% identical), guinea pig SLC3A2 (75% identical), mouse Slc3a2 (75% identical), tropical clawed frog slc3a2 (46% identical), zebrafish slc3a2a (40% identical), zebrafish slc3a2b (40% identical), zebrafish zgc:158423 (38% identical), and 12 more. Paralogues in human: SLC3A1 (27% identical), GBE1 (16% identical), AMY2A (13% identical), AMY2B (13% identical), AMY1A (12% identical), AMY1B (12% identical), AMY1C (12% identical).
Diseases named in the same sentence as SLC3A2 in open-access papers:
SLC3A2 is named in the same sentence as 175 diseases in open-access papers, as found by Europe PMC text mining. Sharing a sentence is not in itself a finding about the gene and the disease. The quoted sentences say what the papers report.
breast cancer (38 papers, 2012 to 2026). A primary or metastatic malignant neoplasm involving the breast. "High co-expression of SLC7A5 and SLC3A2 in breast cancer tissue was significantly associated with aggressive tumour phenotypes, such as increased proliferation, invasion, and metastasis." (PMID 41154605, 2025). "High expression of SLC3A2 protein was found to be associated with poor patient prognosis in breast cancer, but only in the estrogen receptor-positive and triple-negative subtypes, and not in the HER2 positive subtype." (PMID 38253025, 2023). "Since disease network interaction analysis of SLC3A2 from OPENTARGET database showed SLC3A2 strongly associated with breast cancer (BC), we aimed to explore the biological function of SLC3A2 in BC." (PMID 37484811, 2023). "In detail, in independent cohorts for endometrial cancer, lymphoma, colorectal cancer, and breast cancer, cytotoxic T lymphocyte was associated with better overall survival only in samples with lower SLC3A2 expression." (PMID 35992269, 2022). "High SCRIB and SLC3A2 mRNA expression was associated with poor clinical prognosis in ER+ breast cancer patients receiving tamoxifen treatment." (PMID 35501367, 2022). "Previous study reported that SLC3A2 is associated with poor prognostic characteristics and poor survival outcome in breast cancer." (PMID 35057861, 2022). "For instance, breast cancer cell lines seem to depend on SLC3A2 which encodes for the heavy chain subunit of the cystine-glutamate antiporter (xCT system), along with SLC7A11." (PMID 35912247, 2022). "In this study, we report that high SLC7A5/SLC3A2 co-expression is associated with poor clinical outcome in ER+ breast cancer patients, while those in the other combinatorial subgroups showed a better outcome." (PMID 32093034, 2020). "Specifically, patients with SLC7A5+SLC3A2+ tumours were significantly associated with disease recurrence, distant metastasis and a high risk of death from breast cancer (p < 0.05) compared with the other subgroups, which showed better clinical outcome." (PMID 32093034, 2020). "Altogether, these findings indicate that high SLC7A5/SLC3A2 co-expression associates with aggressive features in ER+/HER2− breast cancer, leading to cancer progression and short survival." (PMID 32093034, 2020). "Altogether, these findings indicate that the SLC7A5/SLC3A2 complex implicated in the proliferation of ER+ breast cancer leads to tumorigenesis and the aggressiveness phenotype." (PMID 32093034, 2020). "In this regard, we observed that the SLC7A5+SLC3A2+ subgroup is associated with high levels of mitotic activity in patients with ER+ breast cancer." (PMID 32093034, 2020). "Association of SLC3A2 mRNA with the molecular subtypes was confirmed using the Breast Cancer Gene-Expression Miner v4.0." (PMID 29545595, 2018). "In breast cancer, SLC3A2 expression was found to be associated with poor patient outcomes." (PMID 38705513, 2024). "The TCGA breast cancer cohort study corroborated that the expression of the ferroptosis‐related protein SLC3A2 is positively correlated with TYRO3 expression, and high TYRO3 expression is associated with resistance to PD‐1 inhibitors in breast cancer patients." (PMID 41560416, 2026). "Knockdown of SLC7A5 and SLC3A2 resulted in reduced proliferation of ER+ breast cancer cells and enhanced the sensitivity of ER+ breast cancer cells to tamoxifen." (PMID 41154605, 2025). "In conclusion, our data reveal that targeting estrogen-regulated SLC7A11 and SLC3A2 enhances ferroptosis in ER+ breast cancer, offering a novel therapeutic option for patients with ER+ breast cancer, particularly those with endocrine resistance." (PMID 39833180, 2025). "SCRIB upregulated by estrogen signaling interacts with SLC3A2 to modulate leucine amino acid transport, contributing to the proliferation and tamoxifen resistance of ER+ breast cancer cells." (PMID 39833180, 2025).
breast cancer (continued). "Our study demonstrated that ERα binds to the ERE present in the promoter regions and enhances the transcription of SLC7A11 and SLC3A2, inhibiting ferroptosis and contributing to the growth of ER+ breast cancer cells." (PMID 39833180, 2025). "q-PCR analysis demonstrated that estrogen significantly increased the mRNA levels of SLC7A11 and SLC3A2 in ER+ breast cancer cells." (PMID 39833180, 2025). "SLC3A2 is upregulated in several cancers, such as human osteosarcoma, gastric cancer and breast cancer, and promotes tumor growth through ferroptosis signaling pathway." (PMID 38639872, 2024). "Based on the information from TCGA database, SLC35A2 expression positively correlates with SLC3A2 expression in human breast cancer." (PMID 38639872, 2024). "Another study found that co-expressed SLC7A5/SLC3A2 knockdown inhibited breast cancer cell proliferation and increased sensitivity to the tamoxifen." (PMID 39834939, 2024). "In breast cancer, the stability of the SLC3A2 protein is altered by acidosis which results in ferroptosis in cancer cells." (PMID 38705513, 2024). "WB, Co-IP, cell proliferation assay, Edu staining, ROS and GSH assay and in vivo tumor xenograft assays were performed to verify FKBP1A/SLC3A2 axis in everolimus inducing ferroptosis of breast cancer." (PMID 37484811, 2023). "Overexpression of SLC3A2 can promote tumorigenesis, and SLC3A2 is overexpressed in various cancer cell lines including lung cancer, colon cancer, and breast cancer." (PMID 36733341, 2023). "SLC3A2 expression was detected in ER+ and ER− breast cancer patients’ tissue by immunohistochemistry staining." (PMID 35501367, 2022). "Unexpectedly, the cellular surface protein levels of SLC3A2 are high in ER+ breast cancer cells than in ER− breast cancer cells, like the pattern we had previously reported for surface protein levels of SLC7A57." (PMID 35501367, 2022). "Conversely, knockdown of SLC3A2 (SLC3A2-KD) suppressed cell proliferation in ER+ breast cancer cells in both 2D and suspended culture conditions." (PMID 35501367, 2022). "Considering that SCRIB-P305L mutant interacts with LLGL2, SCRIB works as a scaffold of SLC7A5-SLC3A2 complex to direct the membrane localization of SLC3A2 in ER+ breast cancer cells." (PMID 35501367, 2022). "Unexpectedly, SLC3A2-KD decreased the total protein levels of SLC7A5 in ER+ breast cancer cells, and conversely, SLC7A5-KD reduced total protein levels of SLC3A2." (PMID 35501367, 2022). "To elucidate the role of SLC3A2 in breast cancer cells, we examine the expression levels of SLC3A2 in breast cancer tissues." (PMID 35501367, 2022). "It has been revealed that high SLC3A2 protein expression meant poor breast cancer-specific survival and distant metastasis-free survival." (PMID 35371305, 2022). "Unexpectedly, SCRIB and SLC3A2 form a quaternary complex with LLGL2-SLC7A5 to promote membrane assembly of the SLC7A5/SLC3A2 amino acid transporter complex, which is needed for leucine uptake and proliferation of ER+ breast cancer cells in culture and in vivo." (PMID 35501367, 2022). "For example, SLC3A2 and Ki67 are significantly correlated in NSCLC and associated with poor prognosis in breast cancer." (PMID 36139528, 2022). "The expression of both SLC7A11 and SLC3A2 subunits can be a marker for xCT function and selenoprotein production capacity of breast cancer cells." (PMID 33672555, 2021). "The predictive value of SLC7A5/SLC3A2 co-expression regarding the benefit from endocrine therapy will require further investigation in clinical trials of primary breast cancer treatment." (PMID 32093034, 2020). "We found that proliferation-related genes are highly expressed in a subgroup of patients with high SLC7A5/SLC3A2, and knockdown of SLC7A5/SLC3A2 decreased proliferation of ER+ breast cancer cells." (PMID 32093034, 2020).
breast cancer (continued). "In patients treated with endocrine therapy, high SLC7A5/SLC3A2 co-expression was associated with poor patient outcome, and depletion of SLC7A5/SLC3A2 using siRNA increased the sensitivity of breast cancer cells to tamoxifen." (PMID 32093034, 2020). "Co-expression of SLC7A5/SLC3A2 mRNA within the METABRIC cohort was used to determine the prognostic value in ER+/HER2− breast cancer, whereby the SLC7A5+SLC3A2+ subgroup was associated with poor clinical outcome." (PMID 32093034, 2020). "Our study further establishes the impact of SLC7A5/SLC3A2 co-expression on the clinical outcome and efficacy of adjuvant endocrine treatment in a large cohort of patients with ER+ breast cancer." (PMID 32093034, 2020). "The biological and clinical impact of SLC7A5/SLC3A2 co-expression was assessed in large annotated cohorts of ER+/HER2− breast cancer with long-term follow-up at the mRNA and protein levels." (PMID 32093034, 2020). "This study aims to assess the effects and roles of SLC7A5/SLC3A2 co-expression in predicting responses to endocrine therapy in patients with ER+ breast cancer." (PMID 32093034, 2020). "In this study, we aim to evaluate the predictive value of the co-expression of the SLC7A5/SLC3A2 complex as a clinical marker of benefit from endocrine therapy in early ER+ breast cancer." (PMID 32093034, 2020). "In this study, we showed the clinicopathological significance and prognostic utility of the SLC7A5/SLC3A2 complex in predicting the benefit of endocrine treatment in patients with ER+ breast cancer." (PMID 32093034, 2020). "To investigate whether SLC7A11 and SLC3A2 are involved in ERα-regulated ferroptosis, we examine the effects of knocking down SLC7A11 and SLC3A2 using two different shRNAs in ER+ breast cancer cells." (PMID 39833180, 2025). "Moreover, elevated mRNAs levels of SLC7A11 and SLC3A2 were correlated to decreased overall survival and relapse-free survival rates of breast cancer." (PMID 39833180, 2025). "The mechanism involves the induction of ferroptosis in breast cancer cells through the zinc finger protein an1 type domain 5 (ZFAND5)/ solute carrier family 3 member 2 (SLC3A2) pathway, increasing the concentration of ROS in tumor cells, and reducing the level of GSH248." (PMID 40959280, 2025). "Moreover, SLC7A11 and SLC3A2 levels were elevated in endocrine-resistant breast cancer cells and tumors." (PMID 39833180, 2025). "Additionally, the protein levels of SLC7A11 and SLC3A2 were found to be positively correlated with ERα protein levels in ER+ breast cancer cell lines." (PMID 39833180, 2025). "Overall, considering the expression of SLC7A5/SLC3A2 in breast cancer patients could predict failure in endocrine therapy and guide the choice of other alternative therapies." (PMID 38705513, 2024). "Protein levels of GPX4, SLC7A11, and SLC3A2 in four luminal breast cancer cell lines (MDAMB415, ZR75-1, MCF7, and CAMA1), four basal breast cancer cell lines (MDAMB436, MDAMB231, HCC1937, and HCC1806), and one normal breast epithelial cell line (MCF10A) were concordant with mRNA expression." (PMID 37596261, 2023). "We next investigated the relationship between SLC3A2 and metabolome in ER+ breast cancer cells." (PMID 35501367, 2022). "SLC3A2 is highly expressed in breast cancer and osteosarcoma." (PMID 33672555, 2021). "After showing that SLC7A5/SLC3A2 co-expression was associated with a worse outcome in patients with ER+ breast cancer, we next asked whether SLC7A5/SLC3A2 co-expression correlates with endocrine sensitivity." (PMID 32093034, 2020). "Despite our data demonstrating the prognostic and predictive utility of SLC7A5/SLC3A2 co-expression in ER+ breast cancer, the exact mechanism of how the heterodimeric complex of SLC7A5/SLC3A2 contributes to endocrine resistance is unclear and requires further mechanistic investigations." (PMID 32093034, 2020).